TMEM14DP (transmembrane protein 14D, pseudogene)
Synonyms: bA524O24.3; formerly TMEM14D
Gene: Processed pseudogene on chromosome 10 (68,544,489 to 68,544,833, reverse strand). Ensembl gene ENSG00000214881.
Subcellular location: Membrane